MIR519E (microRNA 519e)
Synonyms: hsa-mir-519e; MIRN519E
Gene: MicroRNA gene on chromosome 19 (53,679,940 to 53,680,023, forward strand). Ensembl gene ENSG00000207810.
Gene Ontology:
Biological process: miRNA-mediated post-transcriptional gene silencing